SPOP (speckle type BTB/POZ protein)
Diseases named in the same sentence as SPOP in open-access papers (continued):
Sharing a sentence is not in itself a finding about the gene and the disease.
leukemia (3 papers, 2021 to 2023). A malignant (clonal) hematologic disorder, involving hematopoietic stem cells and characterized by the presence of primitive or atypical myeloid or lymphoid cells in the bone marrow and the blood. "Together, these results prove that the loss of SPOP can induce BETi resistance in vivo and lead to leukemia cell expansion under BETi exposure." (PMID 37036970, 2023). "Inspired by the consistent BETi-resistance phenotype of SPOP-deficient cells observed in multiple KMT2A-r leukemia cell lines in vitro, we then characterized the resistance phenotype in vivo." (PMID 37036970, 2023). "In summary, we discovered an unappreciated role of SPOP in acquired BETi resistance of KMT2A-r leukemia that cannot be identified through genomic sequencing of large patient cohorts without BETi drug treatment." (PMID 37036970, 2023). "Collectively, these data demonstrated the SPOP-mediated BETi resistance in KMT2A-r leukemia cells." (PMID 37036970, 2023). "By conducting drug treatment–based combinatorial functional CRISPR screens, comprehensive validation with cell lines and patient-derived xenografts (PDXs), and mechanistic studies, we identified the SPOP as a critical gene responsible for BETi resistance in KMT2A-r leukemia." (PMID 37036970, 2023). "The SPOP substrate DAXX typically localizes to promyelocytic leukemia bodies." (PMID 33894201, 2021). "Although genomic SPOP mutation is rarely observed in human leukemia, our preliminary data identified SPOP as an essential gene in BETi-resistant leukemia cells; however, BRD4 and MYC were not direct substrates." (PMID 37036970, 2023). "However, SPOP-knockout cells exhibited mild survival disadvantage upon DMSO treatment for 19 d, indicating that SPOP is required for leukemia cell survival." (PMID 37036970, 2023). "Similar to SPOP, intact DNMT3A has been found to be critical for PML-RARA-driven leukemia 41,42." (PMID 33531470, 2021). "In this study, we found a role of SPOP in acquired BETi resistance of KMT2A-r leukemia that could not be identified through genomic sequencing of large patient cohorts without BETi drug treatment." (PMID 37036970, 2023).
lung squamous cell carcinoma (3 papers, 2018 to 2025). "The results demonstrated consistently lower levels of SPOP expression at both mRNA and protein levels in LUAD and lung squamous cell carcinoma (LUSC) compared to normal tissues, with particularly significant changes observed in LUAD." (PMID 40657370, 2025).
osteosarcoma (3 papers, 2011 to 2022). A usually aggressive malignant bone-forming mesenchymal neoplasm, predominantly affecting adolescents and young adults. "The possible effect of SPOP on NF-κB signaling is supported by a recent report showing that downregulation of SPOP promotes the migratory and invasive abilities of osteosarcoma cells through its regulation of the PI3K/Akt/NF-κB signaling pathway." (PMID 32365080, 2020). "CDK 9 overexpression also increased proliferation of human osteosarcoma cell line U20S2, while CRK, CDK9, DCAF7, NEK6, GNB1, SPOP, and WW2 also increased proliferation in mouse fibroblasts." (PMID 21629697, 2011).
bladder urothelial cancer (2 papers, 2018 to 2022).
breast invasive carcinoma (2 papers, 2022 to 2025). "In 3 representative tumor types with high expression of SPOP and RIPK1, kidney renal clear cell carcinoma, liver hepatocellular carcinoma, and breast invasive carcinoma, this regulatory mechanism remains applicable." (PMID 41122967, 2025).
breast tumor (2 papers, 2022 to 2023). "This is a similar observation to that of a recent study where activated Moesin competes with E3 ligase SPOP to prevent PD-L1 degradation and thereby promotes breast tumor progression." (PMID 37736741, 2023).
Ewing sarcoma (2 papers, 2021 to 2025). A small round cell tumor that lacks morphologic, immunohistochemical, and electron microscopic evidence of neuroectodermal differentiation. "Together, these data further support a physiological role of SPOPCUL3 in targeting EWS–FLI1 for degradation and suggest that Ewing sarcoma tumors may inactivate SPOP‐mediated EWS–FLI1 degradation through CUL3 mutations to promote Ewing sarcoma growth." (PMID 34060252, 2021). "In conclusion, targeting the SPOP/OTUD7A-EWS-FLI1 axis offers a promising therapeutic strategy for Ewing sarcoma, particularly in cases driven by the EWS-FLI1 fusion protein." (PMID 40521202, 2025). "Since SPOP/CK1 destabilizes EWS–FLI1, activation of SPOP/CK1 could offer a therapeutic strategy to treat Ewing sarcoma." (PMID 34060252, 2021). "Speckle‐type POZ protein (SPOP) and OTU domain‐containing protein 7A (OTUD7A) are identified as the bona fide E3 ligase and deubiquitinase, respectively, that control EWS–FLI1 protein turnover in Ewing sarcoma." (PMID 34060252, 2021).
gynecologic cancers (2 papers, 2018 to 2025). "In breast and gynecologic cancers, multiple lines of evidence suggest that SPOP primarily functions as a tumor suppressor, influencing cell proliferation/migration/invasion 42,69,70, immune escape 71-73, MAPK/ERK signaling 74, and metabolic regulation." (PMID 40521202, 2025). "What is worthy of mentioning is that SPOP mutation in gynecological malignant tumor is not uncommon (18% in endometrial clear cell carcinoma, 14% in carcinosarcoma)." (PMID 29986747, 2018).
lymphoma (2 papers, 2021 to 2022). A malignant (clonal) proliferation of B- lymphocytes or T- lymphocytes which involves the lymph nodes, bone marrow and/or extranodal sites. "Second, the SPOP-mediated K48-linked ubiquitination and degradation of MyD88 were dominant in Aifantis’s cell system, and triggered nondegradative mixed-linkage ubiquitination of MyD88 was dominant in the human lymphoma cell lines used in Wang’s study." (PMID 32235916, 2021). "A recent study showed that SPOP triggered mixed-linkage ubiquitination of MyD88 in human lymphoma cells and mouse HSCs, suggesting that the SPOP-MyD88 pathway plays a critical role in hematopoietic neoplasms." (PMID 35874839, 2022).
Pca (2 papers, 2021). "Overall, our findings confirm that G3BP1 is abundantly expressed in aggressive PCa samples and strongly associated with the accumulation of SPOP substrates AR and TRIM24." (PMID 34795264, 2021). "Given that in PCa the SPOP mutations are hemizygous in nature and G3BP1 binds to wild-type SPOP but not SPOPF133V mutant, our results suggest that G3BP1 adds another layer of negative regulation of remaining SPOPWT allele on top of the existing tumor-promoting effect of SPOPF133V." (PMID 34795264, 2021). "In vivo and in vitro experiments carried out revealed a novel BET and CBP inhibitor, NEO2734, is effective against the JQ1-resistant SPOP hotspot mutant, which could proceed further to clinical trials for effective anti-cancer therapy against SPOP-mutated PCa patients." (PMID 33394237, 2021). "Taken together, these findings clearly demonstrated that G3BP1 regulates a molecular program where the SPOP ubiquitin ligase function is compromised, resulting in increased accumulation of SPOP substrates that drive migration and invasion of PCa cells." (PMID 34795264, 2021). "Our study supports a fundamental role of G3BP1 in disabling the tumor suppressive Cul3SPOP, thus defining a PCa cohort independent of SPOP mutation." (PMID 34795264, 2021). "Therefore, there are significantly more PCa that are defective for SPOP ubiquitin ligase than previously appreciated, and these G3BP1high PCa are more susceptible to AR-targeted therapy." (PMID 34795264, 2021). "We propose that G3BP1high may represent a PCa patient cohort characterized by compromised tumor-suppressive SPOP ubiquitin ligase and hyper-activated AR." (PMID 34795264, 2021). "Next, we attempted to determine whether silencing of G3BP1 can reinvigorate the SPOP function, so that SPOP can degrade its substrates that are responsible for PCa progression." (PMID 34795264, 2021). "To assess G3BP1-SPOP signaling in SPOP-mutant PCa, we generated Pten−/−-SPOPF133V mPECs with doxycycline (DOX)-inducible G3BP1 as a model of G3BP1high SPOPF133V PCa." (PMID 34795264, 2021). "Next, we tested whether negative regulation of SPOP ubiquitin ligase activity by G3BP1 would promote migration and invasion of PCa cells." (PMID 34795264, 2021). "Future studies should address whether it is the G3BP1-mediated suppression of SPOP or other SPOP-independent G3BP1 functions, such as stress granule formation that facilitates PCa progression to higher grade tumors." (PMID 34795264, 2021). "Notably, G3BP1 protein levels were found to be high in PCa tumors featuring either SPOPWT or SPOPMut, indicating that PCa-associated G3BP1 overexpression is independent of SPOP mutation status." (PMID 34795264, 2021).
Salmonella Infections (2 papers, 2020). Infections with bacteria of the genus SALMONELLA. "We also demonstrated that SPOP is critical for regulating NF-κB signaling and innate immune response in Salmonella infection." (PMID 32365080, 2020).
scleroderma (2 papers, 2018 to 2022). Scleroderma is a rare autoimmune connective tissue disorder characterized by abnormal hardening of the skin and, sometimes, other organs. "The speckle-type POZ protein (SPOP) was first cloned as a novel antigen from a scleroderma patient in 1997, and was identified as an E3 ubiquitin-protein ligase that mediates ubiquitination and degradation of targeted proteins through proteasomal pathways." (PMID 36115849, 2022). "Speckle-type POZ protein (SPOP) has been recognized as a novel nuclear speckle-type protein in human cells and an autoantigen in scleroderma patients." (PMID 30607139, 2018).
thyroid (2 papers, 2016 to 2021). "SPOP, NF1, BRIP, CNOT1, KMT2C and STAG2 mutations previously identified in PTC might be involved in thyroid tumorigenesis in a type-nonspecific manner." (PMID 27626165, 2016).
triple-negative breast carcinoma (2 papers, 2021 to 2022). An invasive breast carcinoma which is negative for expression of estrogen receptor (ER), progesterone receptor (PR), and human epidermal growth factor receptor 2 (HER2). "LINC01638 interacts with c-Myc, protecting it from the speckle-type BTB/POZ protein (SPOP)-mediated ubiquitination and degradation, with the subsequent upregulation of AEG-1 and Twist1, promoting epithelial–mesenchymal transition (EMT) in triple-negative breast cancer cells." (PMID 33918653, 2021).
viral infections (2 papers, 2023 to 2025). "Nevertheless, the extent to which SPOP regulates viral infection and the underlying mechanisms involved remain undisclosed." (PMID 37796126, 2023).
cholangiocarcinoma (1 paper, 2024). A carcinoma that arises from the intrahepatic biliary tree (intrahepatic cholangiocarcinoma) or from the junction, or adjacent to the junction, of the right and left hepatic ducts (hilar cholangiocarcinoma). "The SPOP transcriptional expression profiles among Cholangiocarcinoma (CHOL) and Liver hepatocellular carcinoma (LIHC) were revealed to be significantly downregulated compared with their para-cancer tissues." (PMID 39074086, 2024).
colorectal tumor (1 paper, 2020). "A study on colorectal tumor has validated that the upregulation of the hedgehog signaling pathway in colorectal tumor mediated by SPOP hypermethylation promotes tumor migration." (PMID 32528944, 2020). "SPOP methylation rate is correlated with colorectal tumor survival." (PMID 32528944, 2020).
diabetes (1 paper, 2020). "Four of the nine validated lncRNAs had predicted mRNA targets related to 32 genes, of which SPOP and DOCK6 have been shown to be associated with diabetes." (PMID 33299893, 2020).
enterovirus infection (1 paper, 2023). "This would provide a potential basis for the inhibition of enterovirus infection by SPOP." (PMID 37796126, 2023).
esophageal adenocarcinoma (1 paper, 2023). A malignant tumor with glandular differentiation arising predominantly from Barrett mucosa in the lower third of the esophagus. "One research revealed that c-Myb enhanced tumor immune escape via targeting miR-145-5p/SPOP/PD-L1 pathway in esophageal adenocarcinoma cells." (PMID 36733484, 2023). "Specifically, c-Myb increased miR-145-5p expression and in turn reduced SPOP and regulated PD-L1, leading to suppression of T cell functions and induction of immune escape in esophageal adenocarcinoma cells." (PMID 36733484, 2023).
genital prolapse (1 paper, 2019). "The high prevalence of sPOP in this study was contradictory to most earlier reports, which have shown that genital prolapse is rare in nullipara." (PMID 29934770, 2019).
hepatic (1 paper, 2023). "With SPOP overexpressing, 25 DisGeNET with padj <0.05 were identified, including neoplasm invasiveness, undifferentiated carcinoma, hepatic methionine adenosyltransferase deficiency, steatohepatitis, and so on." (PMID 37941785, 2023).
invasive ductal carcinoma (1 paper, 2022). "Among the 58 invasive ductal carcinoma specimens, nearly half of the samples (44.8%, 26/58) displayed a reduced SPOP expression along with increased TWIST1, whereas one-third (32.8%, 19/58) of tumors with higher SPOP had lower TWIST1 and 12.1% of tumors had no changes in either one." (PMID 36115849, 2022).
kidney tumor (1 paper, 2019). "Interestingly, SPOP expression did not affect the average tumor size or weight of 769-P (data not shown), suggesting SPOP may be only involved in the early stage of kidney tumor formation." (PMID 30237511, 2019).
lentivirus infection (1 paper, 2022). Virus diseases caused by the Lentivirus genus. "Conversely, SPOP overexpression by lentivirus infection significantly shortened the half-life of CHAF1A protein." (PMID 35773729, 2022).
meningioma (1 paper, 2021). A generally slow growing tumor attached to the dura mater. "C10orf112-PLXDC2 fusion, recently associated with the progression of meningioma, co-occurred in one sample with SPOP variant." (PMID 34680332, 2021).
microcephaly (1 paper, 2022). A congenital or acquired developmental disorder in which the circumference of the head is smaller than normal for the person's age and sex. "Therefore, if a SPOP mutation reduces BET expression due to function acquisition, neuronal differentiation will be affected, causing microcephaly." (PMID 36259278, 2022).
Osteopenia (1 paper, 2025). Osteopenia is a term to define bone density that is not normal but also not as low as osteoporosis. "The pathway's therapeutic vulnerability emerges through SPOP‐GLI3 regulatory axis manipulation, where SPOP depletion‐induced osteopenia and brachydactyly are rescued by GLI3 repressor attenuation." (PMID 40857061, 2025).
ovarian clear cell cancer (1 paper, 2018). An invasive malignant neoplasm that arises from the ovary and is characterized by a predominance of clear and hobnail malignant epithelial cells. "In addition, WES showed that it harbors concurrent ARID1A–PIK3CA mutations and SPOP mutation, also with ZNF217 amplification, which will be an ideal tool for mechanism research of ovarian clear cell carcinoma." (PMID 29986747, 2018).
ovarian serous adenocarcinoma (1 paper, 2021). An adenocarcinoma that arises from the ovary and is characterized by the presence of malignant epithelial cells that, in well differentiated tumors, resemble the epithelium of the fallopian tube or, in poorly differentiated tumors, show anaplastic features and marked nuclear atypia. "The statistical results revealed that the expression of SPOP was significantly higher in ccRCC and ovarian serous adenocarcinoma tissues than in the corresponding adjacent normal tissues, while the distribution of SUFU was the opposite." (PMID 34021128, 2021).
pancreatic adenocarcinoma (1 paper, 2024). "Meanwhile, the associations between SPOP mRNA expression and histologic grade were calculated and consequences presented that SPOP mRNA expression level was correlated to grades in GBMLGG, OV, Pancreatic adenocarcinoma (PAAD)." (PMID 39074086, 2024).
sarcoma (1 paper, 2021). A usually aggressive malignant neoplasm of the soft tissue or bone. "The deubiquitinase OTUD7A antagonizes SPOP function to stabilize EWS–FLI1, revealing OTUD7A as a new Ewing‐sarcoma‐growth‐dependent gene." (PMID 34060252, 2021).
Stomach adenocarcinoma (1 paper, 2020). "ADAMTS9‐AS2 expression was positively correlated with the SPOP expression in GC tissues from Stomach adenocarcinoma (STAD) patients in the TCGA data by using the R package." (PMID 32160650, 2020).
thyroid tumor (1 paper, 2021). A benign or malignant neoplasm affecting the thyroid gland. "Despite SPOP being the most commonly mutated tumor suppressor gene in prostate and its variants being highly prevalent in other human cancers, the p.P94R variant has been recurrently found only in thyroid tumors and its role has yet to be determined." (PMID 34680332, 2021). "Altogether, SPOP p.P94R may be an early stage tumor variant that requires cooperation with other drivers in the pathogenesis of thyroid tumors and so we believe it should be further investigated." (PMID 34680332, 2021). "SOS1 and SPOP have been previously found mutated in thyroid tumors negative for RAS and BRAF mutations and in several types of cancers such as prostate, lung, and colon." (PMID 34680332, 2021).
uterine tumor (1 paper, 2017). "CRHR1 has also been reported fused with CENPP, KIA0100, and SPOP, in one breast, cervical, and uterine tumor, respectively." (PMID 28423358, 2017).